ZNF613 (zinc finger protein 613)
Description:
May be involved in transcriptional regulation.
Synonyms: FLJ13590
Tractability: No criterion of Open Targets' tractability assessment is met for any kind of drug.
Gene: Protein-coding gene on chromosome 19 (51,927,147 to 51,948,759, forward strand). Ensembl gene ENSG00000176024.
Subcellular location: Nucleus
Subcellular location (Human Protein Atlas): Nucleoplasm; Vesicles
Pathways (Reactome):
Gene expression (Transcription): Generic Transcription Pathway
Gene Ontology:
Molecular function: protein binding; DNA-binding transcription factor activity; RNA polymerase II cis-regulatory region sequence-specific DNA binding
Biological process: regulation of transcription by RNA polymerase II; regulation of DNA-templated transcription
Cellular component: nucleus
Genetic constraint (gnomAD): Loss-of-function variants: 10 observed, 15.3 expected, observed/expected ratio (o/e) 0.65, 90% interval 0.4 to 1.11. The upper end of that interval is the gene's LOEUF score, 1.11, which puts it in group 4 of 6, group 1 being the genes least tolerant of losing a copy. Missense variants: 656 observed, 773.01 expected, observed/expected ratio (o/e) 0.85, 90% interval 0.8 to 0.9. Synonymous variants: 228 observed, 264.07 expected, observed/expected ratio (o/e) 0.86, 90% interval 0.77 to 0.96.
Homologues: Orthologues: chimpanzee ZNF613 (99% identical), macaque ZNF613 (96% identical), rabbit ZNF613 (80% identical), pig ZNF613 (76% identical), Drosophila melanogaster CG14442 (5% identical), Drosophila melanogaster CG14440 (4% identical). Paralogues in human: ZNF350 (54% identical), ZNF649 (52% identical), ZNF567 (41% identical), ZNF382 (36% identical), ZNF564 (29% identical), ZNF639 (14% identical), IKZF1 (13% identical), IKZF4 (13% identical), IKZF2 (12% identical), IKZF3 (12% identical), ZNF821 (9% identical).
Diseases named in the same sentence as ZNF613 in open-access papers:
ZNF613 is named in the same sentence as 1 disease in open-access papers, as found by Europe PMC text mining. Sharing a sentence is not in itself a finding about the gene and the disease. The quoted sentences say what the papers report.
cancer (1 paper, 2021). A tumor composed of atypical neoplastic, often pleomorphic cells that invade other tissues. "Finally, OV_sBRCA2 was characterized by the up-regulation of zinc finger proteins (ZNF613, ZNF329, ZNF530, ZNF347), a gene family known to be involved in pathways of carcinogenesis, cancer progression, and metastasis formation." (PMID 33525353, 2021).